KRAS (KRas proto-oncogene, GTPase)
Diseases named in the same sentence as KRAS in open-access papers (continued):
Sharing a sentence is not in itself a finding about the gene and the disease.
metastatic colorectal cancer (continued). "The aim of this study was to investigate the efficacy and safety of first-line panitumumab plus folinic acid, 5-fluorouracil and irinotecan (FOLFIRI) in patients with wild-type KRAS and wild-type NRAS metastatic colorectal cancer (mCRC)." (PMID 29587749, 2018). "International guidelines made RAS (KRAS and NRAS) status a prerequisite for the use of anti-EGFR agents for metastatic colorectal cancer (CRC) patients." (PMID 29755687, 2018). "In the HERACLES-A trial, 33 KRAS exon 2 WT, HER-2 positive metastatic colorectal cancer patients were treated with a combination of lapatinib and trastuzumab, achieving an overall response rate of 30%, with two complete responders." (PMID 29652830, 2018). "For example, patients with metastatic colorectal cancer who have KRAS mutations would not be expected to respond to anti-EGFR therapies such as cetuximab, whereas patients with metastatic melanoma who have a BRAF mutation may be suitable for anti-BRAF therapies such as vemurafenib and dabrafenib." (PMID 28114309, 2017). "In 2014 the European Medicines Agency included exon 2, 3 and 4 KRAS and NRAS testing for the selection of metastatic colorectal cancer (mCRC) patients eligible for the therapy with anti-EGFR monoclonal antibodies." (PMID 26335936, 2015). "This evidence was rapidly followed by a directive of the European Medicines Agency (EMA) that restricted the use of panitumumab (Vectibix®) and cetuximab (Erbitux®) to patients with KRAS and NRAS (exon 2, 3 and 4) wild type metastatic colorectal cancer." (PMID 26435479, 2015). "That is mutated KRAS has the potential to prevent the mechanism of action of the main drugs that treat metastatic colorectal cancer, which may explain the low results and the absence of a statistically significant difference observed in the mutated KRAS subgroup." (PMID 26557880, 2015). "Although cetuximab and panitumumab show an increased efficacy for patients with KRAS-NRAS-BRAF and PI3KCA wild-type metastatic colorectal cancer, primary resistance occurs in a relevant subset of molecularly enriched populations." (PMID 24691006, 2014). "First-line triplet chemotherapy plus bevacizumab (FIr-B/FOx) can improve efficacy of metastatic colorectal cancer (MCRC), KRAS wild-type and mutant." (PMID 24715238, 2014). "The most effective chemotherapy regimens used in the metastatic colorectal cancer setting involve combinations of a fluoropyrimidine with oxaliplatin or irinotecan and a monoclonal antibody targeting VEGF or, in patients with wild-type KRAS, targeting EGFR." (PMID 40004631, 2025). "Cetuximab plus FOLFIRI improved overall survival compared with bevacizumab plus FOLFIRI in KRAS wild-type metastatic colorectal cancer (mCRC) in FIRE-3, but no corresponding benefit was found for progression-free survival." (PMID 33154570, 2021). "Therefore, in the present study, we provide new insight on the role of KRAS and BRAF, not only as prognosis biomarkers, but also as first line standard chemotherapy response biomarkers in metastatic colorectal cancer." (PMID 31952366, 2020). "Approximately 30% of patients with sCRC have KRAS mutations and are resistant to EGFR inhibitors, and up to 50% of metastatic colorectal cancer (mCRC) cases with KRAS wild-type (WT) do not respond to anti-EGFR therapies." (PMID 30344942, 2018). "From our analysis we conclude that as regards KRAS in metastatic colorectal cancer (mCRC) treated with an anti-EGFR antibody a neutral evolution model and not KRAS mutations provides a greater understanding of the clinical outcome." (PMID 28981524, 2017). "Mutations in KRAS and NRAS genes are negative predictors of anti-EGFR therapies response in metastatic colorectal cancer." (PMID 25859555, 2015).
metastatic colorectal cancer (continued). "The combination of lenalidomide and cetuximab appeared to be well tolerated but did not have clinically meaningful activity in KRAS-mutant metastatic colorectal cancer patients." (PMID 24244261, 2013). "The association between KRAS mutation and the lack of benefit of anti-EGFR monoclonal antibodies, such as cetuximab and panitumumab, in metastatic colorectal cancer has been established." (PMID 24179496, 2013). "Activating somatic mutations in the KRAS oncogene is an example of a biomarker, which predicts non-response to therapies targeting the epidermal growth factor receptor (EGFR) in metastatic Colorectal Cancer (mCRC)." (PMID 23173730, 2012). "National and European guidelines recommend a first-line doublet or triplet chemotherapy regimen as induction therapy associated with targeted therapy depending on the KRAS, NRAS and BRAF status for patients with pMMR/MSS non-resectable metastatic colorectal cancer." (PMID 39796718, 2024). "From a prognostic standpoint, our previous report highlights the significant negative prognostic impact of pooled mutations involving KRAS p.G12C and p.G12S in patients with mCRC (STORIA study: Study of Ras mutations prognostic value in metastatic colorectal cancer)." (PMID 37509241, 2023). "The “Regorafenib for patients with metastatic colorectal cancer who progressed after standard therapy” study (CONSIGN study) confirmed these results and found an overall median PFS of 2.7 months (95% CI), 2.5 months for KRAS mutant tumors, and 2.8 months for KRAS wild-type tumors." (PMID 37296986, 2023). "Drugs targeting the epidermal growth factor receptor (EGFR), such as cetuximab and panitumumab, have been prescribed for metastatic colorectal cancer (CRC), but patients harboring KRAS mutations are insensitive to them and do not have an alternative drug to overcome the problem." (PMID 30459318, 2018). "Given this evidence, the KRAS mutation testing is approved by food and drug administration (FDA) for treatment of KRAS mutation-negative (wild-type), EGFR-expressing metastatic colorectal cancer, and is required by European medicines agency (EMA) before the initiation of anti-EGFR therapy." (PMID 30406144, 2018). "However, recent studies showed that KRAS G13D mutation and codon 12 mutations are actually not created equal in predicting clinical outcomes of anti-EGFR therapy in metastatic colorectal cancer (mCRC) patients." (PMID 23874486, 2013). "Treatment success using Cetuximab and Panitumumab for treatment of metastatic colorectal cancer depends on a nonmutated KRAS gene; the treatment is ineffective if the KRAS gene has any mutations, which leads to an activated G-protein even in absence of the ligand, like the epidermal growth factor." (PMID 21197450, 2010). "Therefore, anti-EGFR antibody treatment was only indicated when patients had no mutations in KRAS or BRAF until recently, combination treatment of cetuximab with encorafenib and binimetinib was approved for the treatment of patients with metastatic colorectal cancer harboring a BRAF V600 E mutation." (PMID 35035479, 2022). "Furthermore, low- but not high-level EGFR protein expression on KRAS wild-type metastatic colorectal cancer cells may be a prerequisite for successful anti-EGFR antibody therapy." (PMID 32155907, 2020). "Patients with metastatic colorectal cancer whose disease has progressed on oxaliplatin- and irinotecan-containing regimens may benefit from EGFR-inhibiting monoclonal antibodies if they do not contain mutations in the KRAS gene (are “wild type”)." (PMID 27246726, 2016).
metastatic colorectal cancer (continued). "In a randomized phase-II trial for metastatic colorectal cancer patients who were refractory or intolerant to standard chemotherapies, TAS-102 also improved overall survival regardless of the KRAS tumor status." (PMID 25812794, 2015).
melanoma (423 papers, 2005 to 2026). A malignant, usually aggressive tumor composed of atypical, neoplastic melanocytes. "While KRAS mutations in cutaneous melanoma occur less frequently than BRAF or NRAS mutations, KRAS-linked signaling has garnered attention in other malignancies and exhibits the potential to influence melanoma cell proliferation and phenotypic plasticity." (PMID 40607411, 2025). "The analysis revealed a significant enrichment of KRAS signaling pathways, indicating the potential involvement of molecular mechanisms associated with KRAS pathway activity in melanoma initiation and progression." (PMID 40607411, 2025). "In cases of brain metastases related to melanoma, the overall survival of the patient was found to be reduced in tumors presenting the KRAS mutation." (PMID 40362343, 2025). "Unfortunately, therapies targeting BRAF mutations in melanoma or KRAS mutations have shown limited efficacy in patients with NRAS-mutated tumors." (PMID 39940799, 2025). "NRAS mutations are present in approximately 20% of human melanomas, whereas HRAS and KRAS mutations occur in only 1% and 2% of melanomas, respectively." (PMID 40076927, 2025). "Among them, SRC activation has been implicated in resistance to drugs targeting the MAPK pathway, including EGFRi in KRAS-mutated CRC or BRAFi in BRAF-mutated melanoma." (PMID 40481178, 2025). "The prevalence of mutations was found to be relatively infrequent (i.e. alteration frequency <10%) across most tumour types except endometrial cancer and melanoma, compared to known oncogenic mutations such as KRAS or PIK3CA." (PMID 39746898, 2025). "The activation of KRAS signaling pathways is implicated in melanoma progression, yet its role in shaping the tumor microenvironment, particularly in macrophage infiltration, remains poorly understood." (PMID 40607411, 2025). "KRAS mutations are present in up to 2% of MM and are integral to the development of melanoma in a mouse model." (PMID 41001300, 2025). "Identification of Genes Associated with KRAS Pathway Activity: A set of 22 genes linked to KRAS signaling was identified, correlating with patient survival outcomes in melanoma." (PMID 40607411, 2025). "Although the current study provides valuable insights into KRAS-associated immunomodulation and the prognostic relevance of macrophage biology in melanoma, several limitations warrant acknowledgment." (PMID 40607411, 2025). "This study showed that equine malignant melanoma (EMM) cells (MelDuWi) harbor the KRAS p.Q61H mutation, while canine malignant melanoma (CMM) cells (cRGO1 and cRGO1.2) carry NRAS p.G13R." (PMID 38397192, 2024). "It is also worth mentioning that KRAS mutations have been recently linked with an increased propensity of melanoma tumors to metastasize to the brain and, therefore, envisioned as valuable biomarkers of patient risk stratification in clinical settings." (PMID 38396984, 2024). "Activating mutations in the KRAS gene have been identified in melanoma and can lead to the constant activation of the RAS-RAF-MEK-ERK-MAPK pathway." (PMID 37504268, 2023). "Other KRAS mutations, such as Q61K and Q61R have also been identified in melanoma, although they are less common." (PMID 37504268, 2023). "In vivo studies using colorectal, lung, and melanoma (NRASQ61K SKMel-30) models showed dose-dependent tumor growth inhibition across KRAS- and NRAS-mutated tumors." (PMID 37370834, 2023). "Amongst HRAS-mutant melanomas, 42% carried a co-altered NF1 mutation, significantly greater than in KRAS-/NRAS-mutant melanoma and other HRAS-mutant cancers (p<0.05)." (PMID 37503077, 2023). "These mutations result in activation of the KRAS protein and can lead to uncontrolled cell growth and proliferation, contributing to the development and progression of melanoma." (PMID 37504268, 2023).
melanoma (continued). "Nonetheless, the mutational landscape of melanoma clearly influences organ-specific metastasis as KRAS driver mutations were recently associated with brain colonization as first site of metastasis." (PMID 35109875, 2022). "In opposition, variants in HRAS (HRas proto-oncogene, GTPase) and KRAS (KRAS proto-oncogene, GTPase) are less common: 2% and 3%, respectively, of all melanoma." (PMID 36614156, 2022). "Other mutated isoforms of RAS, namely the H- and N-isoforms, have also been implicated in human cancer, e.g. melanoma, bladder cancer, and acute myeloid leukemia, however to a lower extent in comparison to KRAS." (PMID 35965494, 2022). "In other studies, KRAS mutation has been found in melanoma patients who progressed following combined BRAF and MEK inhibition therapy." (PMID 35814395, 2022). "Considering the retrospective nature of this analysis, the prognostic value of KRAS mutations in melanoma remains suppositional." (PMID 35887633, 2022). "KRAS or HRAS mutations are detected infrequently in approximately 5% of melanoma patients, whereas NRAS mutations (NRASmut) are found in about 25% of patients, which makes NRAS the second most frequent mutation type after BRAF in melanoma." (PMID 36551302, 2022). "In total, 28% (3/18) of acral melanomas showed either a KRAS or NRAS mutation (11% KRAS mutation, 17% NRAS mutation)." (PMID 34102999, 2021). "We identified five cases with NRAS mutations (5/11;45%) and two cases with KRAS mutations (2/11;18%) in the melanomas of nasal cavity." (PMID 34102999, 2021). "Nevertheless, the projected number of new melanoma cases with KRAS/HRAS mutations is substantial and is around 2600 persons per year." (PMID 34831002, 2021). "This is the first study to show significant enrichment of KRAS mutations in melanoma brain metastases as well as an association of KRAS mutations with adverse outcomes." (PMID 33024263, 2021). "The initial KRAS-mutated melanoma of patient 2 showed differences in cell size and morphology compared to the first local recurrence, which had a biphasic appearance, while the second local recurrence was similar to the initial tumor." (PMID 34072863, 2021). "The initial KRAS-mutated melanoma of patient 1 (left) showed only minor differences to the KIT-mutated and NRAS-mutated part of the tumor (middle, right)." (PMID 34072863, 2021). "In contrast, the Bayesian model excluded a suggestion from ANOVA of association between KRAS mutation with lenalidomide response in melanoma." (PMID 33274713, 2020). "In the study of the genetic profile of melanoma brain metastases, KRAS mutations were associated with reduced overall survival from brain metastasis resection." (PMID 32637031, 2020). "Only three melanomas from the digits of dogs have been characterised at the genomic level, with two having KRAS mutations and one an NRAS mutation." (PMID 32652526, 2020). "This is supported by the observation of a significantly higher incidence of coexisting KRAS/NRAS/HRAS mutations in melanomas with class-3 mutations." (PMID 31277584, 2019). "Since then, genetic analysis showed an atypicalG464E mutation in the BRAF P loop region, accompanied by an enhancing G12D KRAS common oncogenic mutation which adds to higher c-MYC expression in C8161 melanoma compared to A375 cells." (PMID 30792807, 2019). "In humans, of these family members, malignant melanomas predominantly bear NRAS mutations with only very rare KRAS and HRAS mutations." (PMID 30188888, 2018). "Although only a small subset of melanomas carry KRAS mutations, these mutation have received sizeable attention due their prevalence in other tumour types." (PMID 28097822, 2017).
melanoma (continued). "The susceptibility to Prima-1, 3-BrPA and NAC in MelJuso cells (BRAF wild-type (wt) and NRAS-Q61L mutant) was compared with that of C8161 melanoma with an enhancing KRAS G12D mutation and a G464E mutation in the BRAF P loop region." (PMID 27863474, 2016). "An NSCLC specimen showed an additional KRAS p.V8I (c.22G > A) mutation in the same allele of p.G13D (c.38G > A) mutation (case P10) and a melanoma specimen showed an addition PIK3CA p.P75S (c.169C > T) mutation (case P8)." (PMID 26498038, 2015). "In this study, we also confirmed the antitumor effects of CH5126766 in NRAS-mutated melanoma cells in vivo as well as in vitro, and also in KRAS-mutated cells in vitro." (PMID 25422890, 2014). "Mutations in BRAF, the downstream effector of KRAS are reported in up to 70% of melanoma cancer cell lines and they are highly prevalent in most common cancers with poor prognosis such as malignant melanoma." (PMID 25361007, 2014). "Compared to CRC, KRAS mutations account for only 2% of melanoma cases, and the reason for this remains unknown." (PMID 40447784, 2025). "Few reports show KRAS Q61 mutations in UV-inducible melanoma models." (PMID 38396984, 2024). "Arguably, rapid detection of mutated genes using IHC allows attending clinicians to rationally select targeted therapies for neoplasms known to harbor HRAS, NRAS or KRAS p.Q61R mutations including ameloblastoma, melanoma, colorectal, urothelial and thyroid cancers, among others." (PMID 37901104, 2023). "Some of the most frequently occurring KRAS mutations in melanoma include G12C, G12V, and G12D." (PMID 37504268, 2023). "This supports our hypothesis that canine digital melanomas differ from oral (and mucosal) melanomas at the genetic level, especially regarding the clear difference of detectable KRAS mutations." (PMID 35202309, 2022). "KRAS exon 2 codons 12 and 13 were mutated in 22/86 (25.6%) of the melanomas examined." (PMID 35202309, 2022). "Moreover, an increase in KRAS expression was linked to melanoma progression, and wild-type KRAS was considered a potential target for melanoma." (PMID 36686734, 2022). "NRAS, HRAS and KRAS isoforms are mutated in 15–20%, 2% and 2% of melanomas, respectively." (PMID 36286442, 2022). "It should be noted that melanomas rarely harbor KRAS mutations and more often HRAS mutations." (PMID 34437586, 2021). "In melanoma, mutations in KRAS are rare, only accounting for 1.7% of cases." (PMID 33801965, 2021). "Our analyses suggest that KRAS mutations could help identify patients with primary melanoma at higher risk of brain metastases who may benefit from more intensive, protracted surveillance." (PMID 33024263, 2021). "Similar to melanoma, KRAS is found to be mutated in skin squamous cell carcinoma but at a low rate." (PMID 33801965, 2021). "Although only 2% of SKMs were reported to be associated with KRAS mutations, because of their possible weaker oncogenic activity in melanocytes than the other isoforms, several other papers highlighted the presence of KRAS mutations in melanoma cell lines." (PMID 34769348, 2021). "KRAS, encoding the human cellular homolog of a transforming gene isolated from the Kirsten rat sarcoma virus, plays essential roles in multiple cancer types, including melanoma." (PMID 32101536, 2020). "In melanoma, KRAS mutations are rare (1.7% of our cases) occurring almost exclusively in codon G12." (PMID 32850962, 2020). "Interestingly, KRAS mutations were detected in several mouse melanoma models and melanoma cell lines." (PMID 31717496, 2019). "Finally, other less frequently mutated melanoma genes (KRAS, HRAS, KIT, GNAQ, GNA11) were enriched in tumors wild‐type for BRAF, NRAS, and NF1." (PMID 28267273, 2017). "Finally, KRAS is the rarest mutated proto-oncogene in melanoma (~2% of cases)." (PMID 38396984, 2024).